ZC3HAV1L (ZC3HAV1 like)
Synonyms: C7orf39; MGC14289
Tractability: PROTAC: ubiquitination databases record sites on it.
Gene: Protein-coding gene on chromosome 7 (139,025,706 to 139,036,042, reverse strand). Ensembl gene ENSG00000146858.
Subcellular location (Human Protein Atlas): Cytosol
Gene Ontology:
Cellular component: cytosol
Genetic constraint (gnomAD): Loss-of-function variants: 23 observed, 23.08 expected, observed/expected ratio (o/e) 1, 90% interval 0.72 to 1.41. The synonymous counts are far from expectation, so gnomAD's model fits this gene poorly and the ratio says little. Missense variants: 376 observed, 324.92 expected, observed/expected ratio (o/e) 1.16, 90% interval 1.06 to 1.26. Synonymous variants: 180 observed, 138.52 expected, observed/expected ratio (o/e) 1.3, 90% interval 1.15 to 1.47.
Homologues: Orthologues: chimpanzee ZC3HAV1L (99% identical), macaque ZC3HAV1L (99% identical), pig ZC3HAV1L (85% identical), dog ZC3HAV1L (84% identical), rat Zc3hav1l (77% identical), mouse Zc3hav1l (74% identical), guinea pig ZC3HAV1L (63% identical). Paralogues in human: ZC3HAV1 (38% identical), PARP12 (30% identical), PARP14 (14% identical), TIPARP (10% identical), PARP9 (8% identical), PARP10 (7% identical), PARP15 (4% identical), PARP11 (1% identical).
Diseases named in the same sentence as ZC3HAV1L in open-access papers:
ZC3HAV1L is named in the same sentence as 2 diseases in open-access papers, as found by Europe PMC text mining. Sharing a sentence is not in itself a finding about the gene and the disease. The quoted sentences say what the papers report.
cervical cancer (1 paper, 2021). A primary or metastatic malignant neoplasm involving the cervix. "Furthermore, the expression level of CTU1 and ZC3HAV1L were higher in the advanced T stage patients (P-values = 0.009 and < 0.001 respectively), implying their dangerous roles with the development of cervical cancer." (PMID 34863153, 2021). "It is displayed in kaplan–Meier curves that higher expression level of EEF1D, CTU1, EIF3C, WDR43, NUFIP1, ZC3HAV1L and PRPF40B indicated a lower overall survival of cervical cancer patients." (PMID 34863153, 2021).
colon cancer (1 paper, 2021). "A risk scoring system consisting of eight IRGs (FGFR2, ZC3HAV1L, TNFRSF11B, CD79A, IGHV3-11, IGHV3-21, IGKV2D-30, and IGKV6D-21) was constructed to evaluate the prognosis of colon cancer patients based on multivariate Cox analysis." (PMID 34938284, 2021). "A risk score system consisting of eight immune-related genes (IRGs) (FGFR2, ZC3HAV1L, TNFRSF11B, CD79A, IGHV3-11, IGHV3-21, IGKV2D-30, and IGKV6D-21) was constructed to predict the prognosis of colon cancer patients." (PMID 34938284, 2021).